TKTL1 (transketolase like 1)
Diseases named in the same sentence as TKTL1 in open-access papers (continued):
Sharing a sentence is not in itself a finding about the gene and the disease.
tumor (continued). "Furthermore, TKTL1-expressing tumours may derive an additional selective growth advantage if the synthesis of fatty acids is not reversed by β-oxidation of fatty acids." (PMID 16465194, 2006). "As it is important to have diagnostic tests to distinguish between clinically aggressive and clinically indolent forms of cancer, our findings demonstrate that the expression of TKTL1 may indicate which tumours have invasive behaviour leading to poor patient survival." (PMID 16465194, 2006). "In tumor tissues of KIRC and KIRP patients, the expression levels of these molecules show a strong positive correlation with the expression of TKTL1, whereas there is hardly any significant correlation in KICH." (PMID 38675412, 2024). "In the tumor tissues of KIRP patients, we discovered a robust connection between the expression level of a marker set for Resting Treg and TKTL1 expression." (PMID 38675412, 2024). "Expression levels of TKTL1 and DNaseX/Apo10 in RMS cell lines (RH30, RD) and tumor samples were analyzed by RT-PCR and flow cytometry." (PMID 36009359, 2022). "The expression of differential genes related to PPP, including TKT, TKTL1, PGM1, GPI, FBP2, ALDOA and ALDOC, were all upregulated in WDLPS tumor samples, which were validated by Real-time Quantitative PCR (RT-qPCR)." (PMID 36557266, 2022). "All biomarker levels (TKTL1, Apo10 and GD2) were significantly enhanced after incubation with tumour cells (LAN-1)." (PMID 35864157, 2022). "The present study investigated the expression of biomarkers TKTL1 and DNaseX/Apo10 in RMS cell lines, in tumor samples as well as in blood samples taken from patients with RMS (using the EDIM blood test)." (PMID 36009359, 2022). "Therefore, TKTL1 may become a new molecular target for tumor therapy." (PMID 34922556, 2021). "There is considerable evidence that tumor cells can upregulate the activity of TKT 82 and induce the expression of TKTL1, whose expression has been shown to be increased due to promoter hypomethylation." (PMID 32549751, 2020). "Transketolase (TKT) or transketolase-like protein 1 (TKTL1), enzymes in the PPP, sustains viability of tumor cells and confers resistance to anti-EGFR antibody therapy and imatinib." (PMID 25693144, 2015). "Significant tumor-specific demethylation was found in MAGEA3 (p<0.005), MAGEA12 (p<0.025), MAGEA4 (p<0.018), MAGEA1 (p<0.001), TKTL1 (p<0.025) and MAGEA5 (p<0.007)." (PMID 19997593, 2009). "The discovery is thrilling as it suggests that TKTL1 could potentially control different kinds of immune cells within the tumor microenvironment of KIRC, making TKTL1 a promising candidate for KIRC treatment." (PMID 38675412, 2024). "The tumor purity was significantly negatively correlated with the TKTL1 expression levels in KIRC, but not in KIRP and KICH." (PMID 38675412, 2024). "Due to a limited tumour material availability, not all patients were eligible for assessment of TKTL1 and DNaseX/Apo10 mRNA." (PMID 35864157, 2022). "Besides, the increased expression of transketolase-like 1 (TLKL-1) protein, one of key enzymes involved in the PPP, predicted more malignant phenotype and facilitate the tumor growth especially in hypoxic condition." (PMID 34593007, 2021). "In several tumor entities, transketolase-like protein 1 (TKTL1) has been suggested to promote the nonoxidative part of the pentose phosphate pathway (PPP) and thereby to contribute to a malignant phenotype." (PMID 30044385, 2018). "TKTL1 has recently been used as a biomarker in a blood test based on the epitope detection in monocytes (EDIM) technology, allowing for the non-invasive detection of neoplasia and tumor recurrence, and thereby it has been proposed as a therapeutic target." (PMID 28143530, 2017). "TKTL1 has recently been used as a biomarker in a blood test based on the epitope detection in monocytes (EDIM) technology allowing for the non-invasive detection of neoplasia and tumor recurrence." (PMID 26907172, 2016).
tumor (continued). "A combined score of Apo10+/TKTL1+ led to a sensitivity of 95.8% and a specificity of 97.3% for the detection of carcinomas independent of the tumor entity." (PMID 24304513, 2013). "Transketolase-like 1 (TKTL1) induces glucose degradation through anaerobic pathways, even in presence of oxygen, favoring the malignant aerobic glycolytic phenotype characteristic of tumor cells." (PMID 21980427, 2011). "TKTL1 expression was determined in 33 patients, while VEGRFR-2 expression was analysed in 32 and VEGFR-1 expression in 26 patients only due to scantness of tumour tissue." (PMID 21854597, 2011). "The epigenetic reactivation of TKTL1, H19, MAGEA2, MAGEA3/6, MAGEA4, MAGEA11, GPR17, GRIN1, and C19ORF28, genes located at diverse chromosomal loci, occurs simultaneously in individual primary tumors from multiple tumor types." (PMID 19305507, 2009). "TKTL1 expression was restricted to tumour cells, and the surrounding stromal tissue showed no staining." (PMID 16465194, 2006). "The immunohistochemical analysis of expression of TKTL1 and activated Akt presented here demonstrate that the majority of TKTL1 overexpressing tumours do have activated Akt and therefore not able to perform β-oxidation of fatty acids." (PMID 16465194, 2006). "Here, we provide evidence that TKTL1 mRNA and protein are specifically overexpressed in tumours, whereas TKT and TKTL2 expression are not upregulated." (PMID 16465194, 2006). "Here, we found a strong relationship between the resting Treg marker set and TKTL1 in tumor tissues from KIRP patients, whereas no such association was detected in KIRC, which further confirmed that high expression of TKTL1 resulted in a better prognosis of KIRC patients, but not in KIRP." (PMID 38675412, 2024). "Taken together, under anaerobic circumstances, malignant cells may benefit from TKTL1 expression and the presence or absence of such conditions could account for the inconsistent reports on the significance of TKTL1 in tumor biology." (PMID 30044385, 2018). "Therefore, the proposed link between TKTL1 expression and chemo- and/or radioresistance as well as increased lactic acid formation by tumor cell lines was not confirmed by our results." (PMID 26187043, 2015). "TKTL1 may also lead to hypoxic-independent HIF-1α stabilization and the subsequent overexpression of several glycolytic and angiogenic genes, providing a suitable environment for tumor progression." (PMID 21980427, 2011). "In this context we could also demonstrate that LDH5 expression was positively correlated with the expression of TKTL1, which does not only inhabit a close functional link to LDH5 in the glucose metabolism of malignant tumors but is also an indicator for aggressive tumor biology." (PMID 20385008, 2010). "As a proportion of TKTL1 overexpressing tumours does not express activated Akt, cancer patients with such tumours may benefit from a concomitant inhibition of fatty acid β-oxidation by activation of Akt or inhibition of AMPK." (PMID 16465194, 2006). "In this perspective, we might speculate that the selective block of TKTL1 through the targeting of PPP metabolic pathway could limit neoplastic development in its early stages represented by hyperplastic and benign tumors, arresting tumor progression in its “primum movens”." (PMID 28143530, 2017). "To determine whether TKTL1 expression correlates with clinical outcomes of colon and urothelial cancer patients, we performed a retrospective survey of surgical samples and determined the survival of patients with tumours expressing or lacking TKTL1." (PMID 16465194, 2006). "TKTL1 is a key enzyme in the non-oxidative arm of the PPP leading to increased lactate production, acidification of the tumor microenvironment with the destruction of the stroma, thus promoting cell migration and metastasis." (PMID 36009359, 2022). "TKTL1 has been proposed to accelerate the nonoxidative PPP and to contribute to the malignant phenotype in a variety of neoplasms." (PMID 30044385, 2018).
tumor (continued). "Transketolase-like protein 1 (TKTL1), an enzyme of the non-oxidative branch of the PPP, has been found to be upregulated in several tumor types, and is involved in tumor cell proliferation, sensitivity to ROS, and metabolic alteration mediated by TIGAR." (PMID 29805774, 2018). "The lack of correlation between TKTL1 and VEGFR-1/2 expression suggests that many different other mechanisms are involved in tumour growth and metastasis and that a change in tumour metabolism is only one of many alterations." (PMID 21854597, 2011). "Due to the missing significance of TKTL-1, M2PK and GLUT-1, an influence of a glycolytic phenotype is not proved as parameter of the tumor progression of ACC." (PMID 19545368, 2009). "So far, three human transketolase genes have been recognised, and the relative contributions of TKT, transketolase-like-1 (TKTL1), and transketolase-like-2 (TKTL2) to tumour-specific transketolase metabolism have not been investigated." (PMID 16465194, 2006). "The enzymatic properties of TKTL1, its upregulation in tumours, and the absence of upregulation of TKT and TKTL2 indicate that TKTL1 is the transketolase targeted by anti-transketolase drugs." (PMID 16465194, 2006). "Normalised VEGFR-1/-2 expression of patients with LARC was significantly higher in pre-treatment tumour tissue in comparison to the corresponding normal mucosa (VEGFR-1; p = 0.0023 and VEGFR-2; p = 0.0005) but failed to be statistically significant for TKTL1 (p = 0.082)." (PMID 21854597, 2011).
cancer (49 papers, 2006 to 2025). A tumor composed of atypical neoplastic, often pleomorphic cells that invade other tissues. "We examined the associations between TKTL1 expression and levels of immune infiltration in almost forty cancer types." (PMID 38675412, 2024). "TKTL1 has been considered a cancer promoter in previous studies and is closely associated with the initiation, development, and progression of cancer." (PMID 38675412, 2024). "In this study, we also found an association between varying levels of TKTL1 and prognostic potential in different cancers." (PMID 38675412, 2024). "Evidence across several cancer tissues up until now have highlighted that TKTL1 is tightly linked to adaptation to hypoxia and its overexpression has been correlated with resistance to ionizing radiation and chemotherapy as well as to the “Warburg effect”." (PMID 35408935, 2022). "For example, TKTL1 mutations are associated with cancers, making it a promising target for anti-cancer treatments." (PMID 30646877, 2019). "TKTL1, previously postulated to be a pseudogene, encodes a transketolase like-protein that is also linked to cancer." (PMID 30646877, 2019). "Transketolase-like protein 1 (TKTL1) has been implicated in cancerogenesis as its cellular expression levels were reported to directly correlate with invasion efficiency of cancer cells and patient mortality." (PMID 23118983, 2012). "TKTL1 encodes an enzyme that promotes aerobic glycolysis, an inefficient mode of ATP production found in cancer cells." (PMID 23028369, 2012). "After observing the correlation between the expression level of the TKTL1 and immune infiltration levels in various forms of cancer, our subsequent focus was to examine the specific types of cancers where TKTL1 is associated with prognosis and immune infiltration." (PMID 38675412, 2024). "The high expression of TKTL1 was associated with reduced drug sensitivity of cancer cells to seven drugs (6-Thioguanine, Parthenolide, Allopurinol, 6-Mercaptopurine, and Pazopanib), and with increased drug sensitivity of cancer cells to one drug (TYROTHRICIN)." (PMID 36362375, 2022). "However, apparently in contrast with what emerged in our study, in which a higher expression of TKTL1 seemed to be associated with longer OS, this gene could be considered a marker of a poor prognosis in different types of cancers." (PMID 39202425, 2024). "Transketolase and TKTL1 regulate various cancer‐related events, including cancer cell proliferation, metastasis, invasion, epithelial‐mesenchymal transition, chemoradiotherapy resistance, and patient survival and prognosis." (PMID 40956032, 2025). "TKTL1 gene expression was previously correlated to different types of cancer, in which enhanced proliferation was observed." (PMID 40680550, 2025). "It was shown that overexpression of the TKTL1 gene in the process of carcinogenesis protects cancer cells against apoptosis, and the elimination of TKTL1 leads to inhibition of proliferation of malignant cells." (PMID 40680550, 2025). "In recent investigations, Apo10 and TKTL1, which are present in blood macrophages, were discovered and subsequently utilized for detecting various types of human cancers." (PMID 39644404, 2025). "TIMER was used to investigate the relationship between TKTL1 and immune infiltrates in various types of cancer." (PMID 38675412, 2024). "This evidence supports the assertion that the levels of TKTL1 expression play a significant role in human malignancies and can serve as prognostic indicators for specific cancer types." (PMID 38675412, 2024). "Another crucial aspect highlighted by this study is the observed correlation between TKTL1 and diverse immune enrichment in cancers, especially in KIRC." (PMID 38675412, 2024). "Of 90 CTAs validated by RNA sequencing, eight CTAs (DPEP3, EZHIP, MAGEA4, MAGEB2, MAGEC2, PAGE1, PRAME, and TKTL1) were selected for immunohistochemical profiling in cancer tissues from 328 NSCLC patients." (PMID 37341056, 2023).
cancer (continued). "TKTL1 participates in aerobic glycolysis in cancer, contributing to basal membrane destruction and cancer metastasis." (PMID 36781976, 2023). "It is related to poor survival in different cancers, and inhibition of TKTL1 leads to a significant reduction in the proliferation of many cancers." (PMID 36984849, 2023). "The TKTL1 isoenzyme is missing 38 amino acids in the active site and increased expression of TKT and its isoform TKTL1 has been reported in different types of cancers, and is related to malignant transformation and poor prognosis." (PMID 35408935, 2022). "Particularly, the EDIM blood test focuses on the detection of two biomarkers, TKTL1 (transketolase-like protein 1) and Apo10 (epitope of DNaseX overexpressed in cancer cells), in CD14+/CD16+ activated monocytes." (PMID 36009359, 2022). "In previous study of TKTL1 in lung and other cancers, patients with a high TKTL1 expression in the primary tumors exhibited a worse prognosis compared to those with a low expression 48-51." (PMID 35711845, 2022). "TKTL1 is a key protein in glucose metabolism in cancer cells and controls the pentose phosphate pathway (PPP)." (PMID 34922556, 2021). "The PanTum Detect test is a novel screening test based on two general markers in cancer, Apo10 and TKTL1, which can be detected with intracellular staining and FACS analysis in CD14+CD16+ gated circulating monocytes using EDIM technology." (PMID 32438648, 2020). "Cancer cells often overexpress TKTL1, which maintains high R5P levels and facilitates nucleotide synthesis and DNA duplication." (PMID 31175280, 2019). "In our study we observed a significant reduction of both G6PD and TKTL1 after pioglitazone treatment according to their role in cancer cells that often lose the balance of oxidation and antioxidant." (PMID 31027492, 2019). "In tumors, the TKTL1 gene leads to a resistance to radical and apoptosis inducing therapies, so cancer patients are unable to benefit from neo-adjuvant chemotherapy and radiation." (PMID 28425973, 2017). "Here, we investigate the expression of TKT and TKTL1 in canine mammary tissues by immunohistochemistry, exploring hyperplastic lesions as well as benign and malignant tumors, including simple and complex types." (PMID 28143530, 2017). "Evidence of biomarkers DNaseX/Apo10 and TKTL1 in macrophages by means of a blood test allowed the early detection of all cancer types analyzed so far." (PMID 28425973, 2017). "Among them, TKTL1 is the isoform specifically upregulated in different human cancers such as head and neck, lung, breast, stomach, colon, nephroblastoma and endometrial cancer." (PMID 26907172, 2016). "Our characterization of the oncogenic role of TKTL1 also sheds light on two largely unexplained phenomena in cancer cell metabolism." (PMID 27391434, 2016). "In conclusion, our study provides unprecedented evidence that TKTL1 plays central roles in major metabolic processes subject to reprogramming in cancer cells and thus identifies TKTL1 as a promising target for new anti-cancer therapies." (PMID 27391434, 2016). "As an initial approach to characterize the relevance of TKTL1 in the metabolism and growth properties of cancer cells, we analyzed 4 cell lines with variable levels of TKTL1 (THP-1 and PC-3S, high expression; HCT-116 and PC-3M, low expression)." (PMID 27391434, 2016). "TKTL1 is upregulated in various cancer cells and tissues, and TKTL1 overexpression in cancer patients is correlated with malignancy, invasiveness, therapeutic resistance and poor prognosis." (PMID 27391434, 2016). "Western blot analyses of five human cancer cell lines demonstrated that JFC12T10 identifies different TKTL1 protein isoforms with molecular weights of 40 and 75 kDa, respectively, the calculated molecular weight of the original TKTL1 protein being 65.4 kDa." (PMID 26187043, 2015).